KLF4 (KLF transcription factor 4)
Diseases named in the same sentence as KLF4 in open-access papers (continued):
Sharing a sentence is not in itself a finding about the gene and the disease.
pulmonary fibrosis (continued). "The fact that PPARγ can inhibit fibroblast activation/differentiation and pulmonary fibrosis suggests that KLF4 induction may be a conserved antifibrotic brake that mediates some of the antifibrotic actions of both cAMP-dependent and PPARγ-dependent agonists." (PMID 35852857, 2022). "Overexpressing of KLF4 inhibited bleomycin-induced pulmonary fibrosis could protect TERT expression and telomere in AECs." (PMID 35508454, 2022). "To further interrogate mechanisms by which KLF4 in PDGFR-β+ cells may induce lung fibrosis, we conducted studies on isolated lung cells." (PMID 34893592, 2021). "KLF4 may be the therapeutic target of pulmonary fibrosis by inhibiting the differentiation of lung resident mesenchymal stem cells." (PMID 33929970, 2021). "Thus, KLF4 plays critical and contrasting roles in the regulation of lung fibrosis depending on the specific mesenchymal cell type: profibrotic in PDGFR-β+ cells and antifibrotic in SMA+ cells." (PMID 34893592, 2021). "KLF4 also plays a vital role in pulmonary hypertension and pulmonary fibrosis." (PMID 31969824, 2019). "Moreover, qRT-PCR and western blotting were performed and confirmed that expression of KLF4 was down-regulated in bleomycin-induced pulmonary fibrosis tissues at both mRNA and protein levels." (PMID 29158503, 2017). "Moreover, results from semi-quantitative analysis of dual staining positive cells showed that overexpression of KLF4 inhibited the proportion of cells undergoing EMT in bleomycin-induced pulmonary fibrosis in vivo." (PMID 29158503, 2017). "This study aimed to examine the role of KLF4 in pulmonary fibrosis and EMT." (PMID 29158503, 2017). "The present study implied that KLF-4 might be a promising target for effective control of the pulmonary fibrosis." (PMID 26839446, 2015). "Interestingly, KLF6 is expressed in the lungs and KLF4 (both KLF4 and KLF6 are phylogenitically related since both belong to group-2 of KLF factors) expression in lung is potentially associated with pulmonary fibrosis and enhanced inflammation of the airway." (PMID 21849067, 2011). "Indeed, Klf4 maintains epithelial homeostasis by regulating EMT (e.g., corneal epithelium) and represents a potential target for pathologies partially caused by EMT (e.g., pulmonary fibrosis, cancer)." (PMID 37180153, 2023). "Besides, telomere length in overexpression group was longer than the control group, indicating that KLF4 could protect telomere length in pulmonary fibrosis." (PMID 35508454, 2022). "Furthermore, these studies delineate mesenchymal cell-type-specific roles of KLF4 in lung fibrosis." (PMID 34893592, 2021). "Moreover, KLF4 inhibited EMT in pulmonary fibrosis model in vivo." (PMID 29158503, 2017). "However, the expression and function of KLF4 in pulmonary fibrosis and EMT of human lung alveolar epithelial cells (AECs) remains unclear." (PMID 29158503, 2017). "It implies that KLF-4 might be a promising target for effective control of the pulmonary fibrosis." (PMID 26839446, 2015). "Several studies have demonstrated that KLF4 expression is significantly reduced in the lung tissues of IPF patients and in bleomycin-induced pulmonary fibrosis models." (PMID 40640934, 2025). "For instance, KLF4 initiates sustained YAP activation and high expression to promote renal fibrosis, which is the opposite of lung fibrosis." (PMID 38105235, 2023). "In this study, we found that the expression of KLF4 was decreased in AECs in IPF patients and bleomycin-induced pulmonary fibrosis mouse models." (PMID 35508454, 2022). "Our data further confirmed that KLF4 is decreased in AECs of IPF lungs and bleomycin-induced pulmonary fibrosis." (PMID 35508454, 2022). "Consistent with the results in human lung tissues, the expression of P16, P21 were increased and KLF4, TERT were decreased in bleomycin-induced pulmonary fibrosis." (PMID 35508454, 2022).
pulmonary fibrosis (continued). "In this study, we demonstrated that the expression of KLF4 was decreased in AECs of human IPF and mouse models of bleomycin-induced pulmonary fibrosis." (PMID 35508454, 2022). "Herein, using bleomycin-induced lung fibrosis, we demonstrate that PDGFR-β+ cells are the major source of myofibroblasts, and KLF4 in PDGFR-β+-derived cells is critical for the accumulation of excess myofibroblasts and ECM." (PMID 34893592, 2021). "Klf4 deletion in PDGFR-β+ cells attenuates bleomycin-induced accumulation of myofibroblasts and lung fibrosis." (PMID 34893592, 2021). "In this study, we demonstrated that the expression of KLF4 was decreased in lung tissues of human IPF and mouse models of bleomycin-induced pulmonary fibrosis." (PMID 29158503, 2017). "Our data showed the first evidence that KLF4 is decreased in lungs of IPF patients and bleomcyin-induced pulmonary fibrosis." (PMID 29158503, 2017). "Decreased expression of KLF4 was first observed in human IPF lung tissues and models of bleomycin-induced pulmonary fibrosis." (PMID 29158503, 2017). "In this study, we describe the novel finding that the expression of KLF4 was decreased in human IPF lung tissues and mouse models of bleomycin-induced pulmonary fibrosis, when compared to the corresponding controls." (PMID 29158503, 2017). "The expression of KLF4 was also observed in normal FVB mouse lung tissue and showed decreased level in bleomycin-induced pulmonary fibrosis model." (PMID 29158503, 2017). "To investigate the possible role of KLF-4 in lung fibrosis, we firstly examined the regulation of TGF-β on the KLF-4 expression in mouse lung epithelial LA-4 cells." (PMID 26839446, 2015). "In the present study, by conducting bioinformatics analysis, we found that Krüppel-like factor 4 (KLF4) expression was decreased in the lung tissues of patients with idiopathic pulmonary fibrosis (IPF) as compared to that in patients with non-IPF." (PMID 37762310, 2023). "Our study found that activation of KLF4 in AECs has a positive effect on the maintenance of TERT and telomere length, which may be a potential target for the treatment of pulmonary fibrosis." (PMID 35508454, 2022). "Over-expression of KLF4 in AECs could protect TERT expression and suppress the development of pulmonary fibrosis in bleomycin-induced mouse models." (PMID 35508454, 2022). "Our results showed that KLF4 could protect TERT expression in AECs by binding with the promoter of TERT, and may become a potential target for the treatment of pulmonary fibrosis." (PMID 35508454, 2022). "Taken together, these findings indicate that, in the context of bleomycin treatment, although Klf4 deletion in PDGFR-β+ cells attenuates lung fibrosis, KLF4 is not required for PDGFR-β+ cell proliferation or differentiation into myofibroblasts." (PMID 34893592, 2021). "KLF4 expression area and intensity was quantified by immunoreactive system (IRS) and it showed that expression of KLF4 was decreased in bleomycin-induced pulmonary fibrosis, compared with controls." (PMID 29158503, 2017). "Krüppel-like Factor 4 (KLF4), a target gene of miR-145, can negatively regulate lung fibrosis." (PMID 28091538, 2017). "Furthermore, ChIP showed that KLF4 protein could bind to the TERT promoter region in MLE-12 cells, suggesting that KLF4 could implicate in pathogenesis of lung fibrosis through regulating TERT transcription in AECs." (PMID 35508454, 2022). "In contrast to PDGFR-β+ cells, KLF4 reduction in α-smooth muscle actin (SMA)+ cells non-cell autonomously exacerbates lung fibrosis by inducing macrophage accumulation and pro-fibrotic effects of PDGFR-β+ cells via a Forkhead box M1 to C-C chemokine ligand 2—receptor 2 pathway." (PMID 34893592, 2021). "However, KLF4’s role in alveolar epithelial cells (AEC) in lung fibrosis is still not clear." (PMID 35508454, 2022). "Thus, we hypothesized that epithelial KLF4 may modulate EMT and lung fibrosis." (PMID 29158503, 2017).
pulmonary fibrosis (continued). "However, it is not clear whether there is an interaction between KLF-4 and PAI-1 in the pulmonary fibrosis." (PMID 26839446, 2015).
colitis (18 papers, 2018 to 2026). Inflammation of the colon. "In DSS-induced colitis, KLF4 overexpression mitigated weight loss and disease activity, preserved colon length, improved histology, and reduced myeloperoxidase activity." (PMID 41918723, 2026). "In our setting, we indeed found that the mRNA levels of goblet cell maturation-related transcription factors Gfi1, Spdef, and Klf4 were higher in Gsdmd-deficient mice than in WT mice during colitis." (PMID 34721422, 2021). "Recently, in a mouse model, we demonstrated that KLF4 plays a protective role against progression of colitis-associated cancer and that decrease in KLF4 levels is associated with increased aggressiveness of the disease." (PMID 32566755, 2019). "Previous studies have elucidated the crucial role of KLF4 in the pathogenesis of sodium taurocholate-induced colitis through its regulation of the NF-κB pathway." (PMID 40471885, 2025). "Mice with an intestinal-cell specific deletion of Klf4 were significantly less sensitive to DSS-induced colitis and showed greater cell proliferation." (PMID 40534851, 2025). "describe a pro-inflammatory role for KLF4 in the intestinal cells of a dextran sodium sulphate (DSS) induced colitis mouse model." (PMID 40534851, 2025). "Consistently, along with ameliorated symptoms and histological damage, mice subjected to DSS-induced colitis receiving 5% red raspberry displayed a greater goblet cell density and increased mRNA levels of Muc2 and Klf4, and HES1 protein content." (PMID 35334805, 2022). "Our experiment showed that DSS-induced colitis decreased the mRNA expression of KLF4, MUC2 and ZO-1 in colon tissue." (PMID 34675239, 2021). "A recent study showed that KLF4 promotes acute colitis in an animal model of inflammatory bowel disease, and that deletion of KLF4 from the intestinal epithelium ameliorates chemically induced colitis." (PMID 29997611, 2018). "The enriched KLF4 has been reported to be a proinflammatory factor because it activates epithelial cytokines in the esophageal squamous epithelium, and KLF4 in the colonic epithelium plays a crucial role in promoting DSS-induced colitis by modulating the NF-κB pathway inflammatory response." (PMID 34829869, 2021).
esophageal squamous cell carcinoma (17 papers, 2016 to 2025). Esophageal squamous cell carcinoma (ESCC) is a type of esophageal carcinoma (EC) that can affect any part of the esophagus, but is usually located in the upper or middle third. "Our findings suggest that loss of KLF4 expression is correlated with a bad outcome in most digestive system cancers, apart from esophagus squamous cell carcinoma (ESCC)." (PMID 29062163, 2017). "In murine esophageal epithelia, Klf4 overexpression causes chronic inflammation which is mediated by activation of NFκB signaling downstream of KLF4, and this esophageal inflammation produces epithelial hyperplasia and subsequent esophageal squamous cell cancer." (PMID 30998758, 2019). "Preliminary data on 52 human samples show that KLF4 expression is low in high grade dysplasia and early stage esophageal squamous cell carcinoma (ESCC), while it becomes prevalent in high grade ESCC." (PMID 39135777, 2024). "KLF4 expression is downregulated in high-grade dysplasia and early esophageal squamous cell cancers, but it increases with advanced cancer stage, and it is negatively connected with survival in these malignancies." (PMID 37176108, 2023). "The overexpression of KLF4 mediates chronic inflammation in the esophagus through the activation of NF-κB signaling, leading to epithelial hyperplasia followed by esophageal squamous cell carcinoma." (PMID 36761967, 2023). "KRT13 is transcriptionally up-regulated by KLF4 to induce differentiation of esophageal squamous cell carcinoma." (PMID 36949761, 2023). "The antitumor effect of KLF4 on esophageal squamous cell cancers (ESCC) is uncertain." (PMID 37031197, 2023). "However, for instance, in esophageal squamous cell carcinoma, KLF4 expression is decreased, and its deletion produces squamous cell dysplasia in mouse models." (PMID 37176108, 2023). "Previous studies identified KLF4 as a target of miR-145-5p in human embryonic stem cells and FSCN1 as a target of miR-143-3p in esophageal squamous cell carcinoma." (PMID 38866991, 2024). "Based on these findings, we propose a model in which KLF4 acts via RHOF to induce NFκB signaling, leading to esophageal epithelial inflammation and esophageal squamous cell cancer." (PMID 30998758, 2019). "KLF4 can also induce NF-κB signaling by activating the ras homolog gene (Rho)-related GTP-binding protein RhoF in esophageal epithelia, and the KLF4-mediated chronic inflammation leads to subsequent esophageal squamous cell cancer." (PMID 36761967, 2023). "The migration and invasion of esophageal squamous cell carcinoma (ESCC) is positively correlated with CDR1as, CDR1as acts as an miR-7 sponge to promote tumor progression by increasing the function of the stem cell marker Klf-4 and homeobox gene B13 (HOXB13)-mediated nuclear factor (NF-κB)." (PMID 32765960, 2020).
non-small cell lung carcinoma (17 papers, 2012 to 2025). A group of at least three distinct histological types of lung cancer, including non-small cell squamous cell carcinoma, adenocarcinoma, and large cell carcinoma. "Previously, it has been shown that increased HOTAIR expression promoted tumor sphere formation in non-small cell lung cancer cells via upregulation of the stem cell-associated markers, including Sox2, Nanog, Oct3/4, c-Myc, β-catenin and Klf4." (PMID 29228709, 2017). "A recent study has shown that glibenclamide, by targeting the K+ channel, modulates the expression of p70S6K and KLF4 in non-small cell lung cancer, and exerts an anticancer effect in both in vitro as well as in in vivo models." (PMID 34569600, 2021). "In non-small cell lung cancer (NSCLC), KLF4 expression is upregulated and closely associated with macrophage infiltration and M2 polarization, while miR-34a-5p targets KLF4 and reverses macrophage polarization, regulating immune molecules such as IL-1β, thus showing therapeutic potential for NSCLC." (PMID 39995670, 2025). "Because the phosphorylation of HSP27 facilitates the ubiquitination and proteasomal breakdown of proteins that drive stemness (including NANOG, OCT4, c-Myc, SOX2, and KLF4) in non-small-cell lung cancer (NSCLC) cells, the inactivation of p38 promotes the expression of CSC characteristics." (PMID 41369386, 2025). "KLF4 inhibits cancer proliferation by stimulating the transforming growth factor beta 1 (TGF-β1)-mediated extracellular signal-regulated protein kinase/stress-activated protein kinase/NF-κB transcriptional program in non-small cell lung cancer." (PMID 36761967, 2023). "However, KLF4 can also function as tumor suppressor and its knockdown can promote migration and invasion of non-small-cell lung carcinoma (NSCLC)." (PMID 35205716, 2022). "Conversely, OTUD1 and OTUD5 deubiquitinated and stabilized KLF4, FHL1, and PTEN, respectively, which effectively suppressed the progression of non-small cell lung cancer (NSCLC)." (PMID 40469292, 2025). "KLF4 is located upstream of the TGF-β pathway and inhibits the growth and migration of non-small cell lung cancer, cutaneous squamous cell carcinoma, and ovarian cancer cells by suppressing TGF-β-induced EMT." (PMID 36761967, 2023). "In non-small cell lung cancer, SIRT6 induced epithelial-to-mesenchymal transition by regulating the snail/KLF4 pathway." (PMID 33198792, 2020). "This study aims to investigate KLF4 and SPARC expression and their correlation with the clinical characteristics of non-small cell lung cancer (NSCLC)." (PMID 23249717, 2012). "However, some studies suggested that KLF4 promoted the progression of non-small cell lung cancer (NSCLC) and this function of KLF4 was related to its subcellular localization." (PMID 37031197, 2023). "In contrast, P38γ and P38δ activation may suppress CSCs development in non-small-cell lung cancer (NSCLC) through promotion of the ubiquitin-mediated degradation of SOX2, OCT4, NANOG, KLF4 and MYC transcription factors that normally contribute to the acquisition of cancer stem cell characteristics." (PMID 35409206, 2022). "In patients with non-small cell lung cancer, higher SPARC expression and lower Kruppel-like factor 4 (KLF4) are detected in tumor tissue compared to non-tumor tissue." (PMID 28969021, 2017).
squamous cell carcinoma (17 papers, 2010 to 2023). A carcinoma arising from squamous epithelial cells. "Studies have figured out that KLF4 has an oncogene effect and can inhibit tumorigenesis in squamous cell carcinoma (SCC) cells by activating SMAD signaling pathway and SOX2 expression." (PMID 32674073, 2020). "Nevertheless, in a contradictory study, KLF4 is required to maintain hTERT expression and telomerase activity in hESC, FaDu (squamous cell carcinoma) and oral epidermoid carcinoma (OECM1) cell lines." (PMID 27153563, 2016). "UAB30 also prevents the formation of squamous cell carcinoma (SCC) in Kruppel-like factor 4 (KLF4) transgenic mouse model, and inhibits tumor growth and increases survival in a murine neuroblastoma xenograft model." (PMID 27078158, 2016). "Conversely, an oncogenic function of KLF4 has also been reported in primary breast ductal carcinoma and squamous carcinoma of oral and skin." (PMID 27835585, 2016). "Although expression of KLF4 is differentiation-dependent in normal epithelia, KLF4 is also commonly overexpressed in squamous cell carcinomas where it can act as an oncogene." (PMID 26431332, 2015). "Consistently, KLF4 knockdown by KLF4-specific small hairpin RNA in human A431 epidermoid carcinoma cells decreased the stem cell population and was accompanied by compromised cell migration." (PMID 22745808, 2012). "In other subtypes of BC, KLF4 may inhibit tumor progression in squamous cell carcinoma or adenocarcinoma." (PMID 37031197, 2023). "Elevated Klf4 overexpression is frequently observed in many types of cancers 85 and overexpressing Klf4 in mice led to squamous cell cancer 86, while the molecular mechanisms remain unclear." (PMID 25116380, 2014). "Moreover, Klf4 has been shown to act as an oncogene cooperating with c-Myc in the transformation of cells, and the inducible expression of Klf4 in mice is sufficient to provoke skin dysplasia and squamous cell carcinoma." (PMID 23451207, 2013). "However, Klf4 is also often over-expressed in keratinocyte-derived squamous cell carcinomas, and initial stages of carcinogenesis, with keratinocyte-specific transgenic expression promoting skin tumor formation." (PMID 20442780, 2010). "However, KLF4 may also function as a tumor promoter in some types of epithelial cell carcinomas, including squamous cell carcinomas (SCC)." (PMID 26431332, 2015). "Importantly, according to published data, the DAPK gene is one of the more often methylated in laryngeal squamous cell carcinoma and ablation of Klf4 in mice results in more severe dysplastic lesions in oral mucosa and higher incidence of squamous cell carcinoma." (PMID 26057471, 2015). "To further test the effect of KLF4 on maintenance of stem cells and on stem cell-related cell migration, we first generated KLF4 knockdown stable cells by transduction with an established KLF4 shRNA, which specifically knocked down KLF4 with a high efficiency, in A431 epidermoid carcinoma cells." (PMID 22745808, 2012). "Also, KLF4 could promote keratin 13 for squamous cell carcinoma differentiation." (PMID 37031197, 2023). "Knocking down PITX1’s DNA binding domain (DBD) significantly inhibited the growth of squamous cell carcinoma, with levels of Ki67 and EdU significantly decreasing, as well as decreased SOX2 expression, but KLF4 expression levels increasing." (PMID 37841446, 2023). "KLF4 expression level are negatively correlated with PITX1 in SCC and suppressing the growth of squamous cell carcinoma in vivo." (PMID 37841446, 2023).